BYSL (bystin like)
Diseases named in the same sentence as BYSL in open-access papers (continued):
Sharing a sentence is not in itself a finding about the gene and the disease.
tumor (11 papers, 2008 to 2025). "We found that NOP14 interacted with some proteins closely related to tumor initiation and development, such as BYSL or NOL6." (PMID 35473611, 2022). "The bystin-like (BYSL) gene is expressed in a wide range of eukaryotes and is closely associated with tumor progression." (PMID 35154253, 2021). "The IR of BYSL was analyzed by immunohistochemistry followed by cell counting in non-tumor brain tissues and GBM tissues (n = 11 for each group)." (PMID 33178594, 2020). "Similarly, silencing BYSL led to decreased tumor volume (P = 0.030) and longer survival time (P = 0.014)." (PMID 33628587, 2021). "In addition, clinical samples were used to detect the expression of BYSL in non-tumor brain tissues and GBM tissues, and to explore the correlation between BYSL and mesenchymal makers (e.g., CHI3L1 and CD44)." (PMID 33178594, 2020). "BAG2 might favor cell proliferation, repress apoptosis and facilitate tumor invasion in HCC, probably through regulation on ribosome biogenesis via genes like WDR12, BYSL, and DCAF13." (PMID 34257542, 2021). "Moreover, inhibiting BYSL using RNA interference significantly decreased HCC cell proliferation in vitro, induced cell apoptosis, and partially arrested the cell cycle, leading to the failure of tumour formation." (PMID 37755981, 2023).
cancer (8 papers, 2019 to 2024). A tumor composed of atypical neoplastic, often pleomorphic cells that invade other tissues. "Importantly, basal cancers express high mRNA levels of genes encoding regulators of ribosome biogenesis such as BYSL, RRS1, RIOK1, POLR1C, and POLR1E (group C)." (PMID 32054925, 2020). "BYSL, involved in rRNA processing and 40S ribosome biogenesis during development and cancer cell proliferation, could play a role in cancer progression." (PMID 39086661, 2024). "Thus, BYSL is generally involved in the malignant progression of cancers." (PMID 33178594, 2020). "Bystin-like (BYSL) is detected in abundance in rapidly proliferating embryo and cancer cells and is evolutionarily conserved across eukaryotes, especially the C-terminus that regulates its nuclear localization." (PMID 32695182, 2020). "Although BYSL and CD3EAP play important roles in human cancers, their specific mechanisms in STS remain unclear and need further exploration." (PMID 34026613, 2021). "BYSL protein is upregulated in HCC and required for nucleologenesis in cancer cell proliferation." (PMID 31151404, 2019).
infection (6 papers, 2010 to 2026). The state of being infected such as from the introduction of a foreign agent such as serum, vaccine, antigenic substance or organism. "We established stable GBM cell lines with overexpression of BYSL by lentivirus-mediated infection in U251 and U87 cells." (PMID 33178594, 2020).
BYSL also shares sentences with these, for which no sentence is quoted: breast tumours (1 paper); Burkitt lymphoma (1); chondrosarcoma (1); diffuse large B-cell lymphoma (1); gastric cancer (1); lung adenocarcinoma (1); microsporidia infection (1); renal carcinoma (1); rhabdomyosarcoma (1); Sepsis (1).